INS (insulin)
Diseases named in the same sentence as INS in open-access papers (continued):
Sharing a sentence is not in itself a finding about the gene and the disease.
diabetes (continued). "The native B:9-23 sequence is required for disease initiation in the NOD mouse as mutation of one amino acid (B16Y>A), a key residue for the MHC-II I-Ag7/T cell receptor interaction, protects NOD mice from diabetes, ablates islet infiltration, and prevents development of insulin autoantibodies." (PMID 36032090, 2022). "Chronic hyperglycemia impairs insulin secretion from pancreatic beta cells in diabetes." (PMID 36376280, 2022). "The weakness in our study could be due to depending on history by patient in regard of insulin use and duration and age of onset of diabetes." (PMID 34874549, 2022). "Also, our sample is representative of the general type 1 diabetes population (wide age and diabetes duration range and a mixture of participants on insulin pump therapy and multiple daily injections)." (PMID 34427840, 2022). "Moreover, a recent study using a mouse model reported that mTOR was differentially involved in tubular autophagy activity via the insulin/mTOR pathway in the presence of nephropathy, depending on the type of diabetes." (PMID 36299884, 2022). "Interestingly, renin inhibition improves insulin sensitivity, glucose tolerance, and insulin secretion in male rodent models of hypertension, diabetes, obesity, and metabolic syndrome." (PMID 35629915, 2022). "If further studies are able to provide glucose regulated insulin secretion by engineered SC, this could lead to treatment of diabetes with a decreased requirement for toxic immunosuppressants." (PMID 36555540, 2022). "Low-dose insulin, combined with other medications, has become the primary treatment for diabetes." (PMID 35502441, 2022). "Compared with the control group, the proportion of INS-positive area in the diabetes model group decreased significantly (from 0.7243 ± 0.0131 to 0.1258 ± 0.0102), whereas the proportion of CD34-positive area increased significantly (from 0.1375 ± 0.00923 to 0.5364 ± 0.0266)." (PMID 36467676, 2022). "Regrettably, there is no therapy or medication available in contemporary medicine that can effectively manage diabetes without causing adverse effects from insulin and oral hypoglycemic drugs." (PMID 35214895, 2022). "Insulin resistance in diabetes may be exacerbated by the inceptor's ability to block insulin signaling." (PMID 36381916, 2022). "More recently, some case reports or case series have been published, detailing non-syndromic and non-autoimmune insulin-dependent forms of diabetes due to the WFS1 mutations." (PMID 36294752, 2022). "Consequently, this can impair insulin biosynthesis and secretion, finally resulting in β cell failure and manifestation of Diabetes mellitus (DM)." (PMID 35075141, 2022). "Third, our patients had a long duration of diabetes and were insulin users." (PMID 35900817, 2022). "At the time of surgery, an inpatient specialist diabetes consulting service was used in the care of 97 patients (55.7%), more commonly if patients had ectopic CS, in those with more severe hyperglycemia, and those treated with insulin." (PMID 34988348, 2022). "Analysis stratified by type of diabetes and duration of insulin." (PMID 35123455, 2022). "Therefore, not only does TD have a significant effect on controlling and reducing hyperglycemia in diabetes, but it also has the potential to decrease the dose of insulin administration." (PMID 35725834, 2022). "Diabetes mellitus (DM) is characterized as a metabolic decompensation that raises blood glucose levels, either by less/non-insulin production by pancreatic β-cells (type 1) or by insulin resistance from cell receptors that require glucose absorption for normal metabolism processes (type 2)." (PMID 35399507, 2022). "This might translate to improvements of insulin action in vivo but perhaps more importantly indicate that H. fomes might help protect structural proteins from the longer-term complications of diabetes." (PMID 35239729, 2022).
diabetes (continued). "In addition, in vivo, rosuvastatin increases Akt phosphorylation, thereby activating systemic insulin sensitivity; this further illustrates that diabetes and dyslipidemias share a range of common molecular targets." (PMID 33828528, 2021). "Thus, we controlled for baseline potential confounders by propensity score matching, including baseline blood glucose, age, gender, duration of diabetes, insulin regimen, and self-monitoring of blood glucose frequency." (PMID 33544081, 2021). "In the present work we address a critical question towards improving diabetes care in resource poor settings, namely whether insulin is stable and retains biological activity in tropical temperatures during a 4-week treatment period." (PMID 33534816, 2021). "PA could therefore represent an attractive alternative to structured exercise training for diabetes patients for improving insulin sensitivity and body composition." (PMID 34659107, 2021). "Notably, patients with diabetes need to be educated about temperature variations and duration of storage of insulin to maintain its efficacy." (PMID 34136581, 2021). "Diabetes mellitus (DM) is a severe chronic disease that occurs either when the pancreas does not produce enough insulin (a hormone that regulates blood glucose) or when the body cannot effectively use the insulin it produces." (PMID 35111135, 2021). "The definitive cure of diabetes may probably come from the biological approaches since they aim to replace the secretion of insulin indefinitely." (PMID 33755854, 2021). "Insulin is commonly used in the management of both type 1 and type 2 diabetes mellitus." (PMID 33556090, 2021). "Given the influence of palmitic acid and oleic acid on insulin signaling, one might have expected to find an increased oleic acid to the palmitic acid ratio in the group with diabetes remission compared to the group with persistent diabetes after RYGB." (PMID 33463892, 2021). "In agreement with those earlier findings and using a second independently generated β3−/− mouse model, recently, it has been shown that β3 deletion protects mice against high-fat-diet-induced diabetes, while β3 overexpression in isolated human islets impaired insulin secretion." (PMID 34440773, 2021). "The association between apelin levels, glucose concentrations, and insulin sensitivity provided evidence that apelin may have a role in the pathogenesis of diabetes mellitus type 2 (DMT2)." (PMID 33540682, 2021). "Among the patients who received insulin, 37.18% (29/78) initiated once diabetes was diagnosed." (PMID 34899594, 2021). "Diabetes hyperglycemia is regulated by insulin level and insulin action in peripherical tissues." (PMID 34572493, 2021). "The interplay between insulin signaling, lipoprotein metabolism, and immune cells has great relevance to inflammatory diseases such as atherosclerosis, one of the major complications of diabetes." (PMID 34717951, 2021). "The insulin signal decreases with age and is a special problem in patients with diabetes mellitus, which may be related to the c-miRNA response." (PMID 34163374, 2021). "Intestinal barrier dysfunction may participate in diabetes mellitus development by increasing intestinal permeability, thus triggering an inflammatory response leading to peripheral insulin resistance and ultimately to diabetes mellitus." (PMID 34084135, 2021). "One study indicated that psoriatic patients with normal glucose tolerance show insulin resistance or impaired insulin sensitivity, which may further develop into diabetes." (PMID 34803716, 2021). "Additionally, consumption of saturated fats can contribute to this diabetes-inducing diet and peripheral insulin insensitivity, adding to the inflammatory state of the body." (PMID 34659962, 2021).
diabetes (continued). "The leading endocrine disorder, Diabetes mellitus, is characterized by an abnormal metabolism and an inappropriately raised amount of serum glucose due to either absolute shortage of insulin or reduced tissue responsiveness to insulin." (PMID 33661976, 2021). "However, the diabetes-induced reduction in circulating insulin levels was significantly higher in mice null for the PRLR." (PMID 33746901, 2021). "Interestingly, natriuretic peptide levels correlate linearly with insulin sensitivity and are often diminished in diabetes and obesity, possibly due to faster clearance." (PMID 34583686, 2021). "My video appt with my diabetes consultant was great as I can download my insulin pump info plus daily blood tests so we could look at it together and do what was necessary." (PMID 34469327, 2021). "Above all, diabetes mellitus, which requires constant insulin administrations, was prioritized." (PMID 34683895, 2021). "According to recent findings, alleviating effects of trehalose in diabetes can result from the improvement of glycemic control and insulin response, increased rate of autophagy, protective effect against oxidative stress, as well as influence on gut microbiota." (PMID 34685538, 2021). "Studies reported that pyridoxine has beneficial effects in diabetes control by reducing diabetes-related disruptions in dopaminergic receptors of liver islet cells and improving insulin signaling and preventing endothelial dysfunction, IR, and intrahepatic fat accumulation." (PMID 33499915, 2021). "Our study may provide evidence of the adverse effect of insulin treatment among patients with COVID-19 and diabetes, especially among those with type 2 diabetes (T2DM), as the subjects in most included studies suffered from T2DM." (PMID 34367067, 2021). "Type 2 diabetes mellitus (T2DM) is a complex metabolic disorder of glucose homeostasis associated with a status of insulin resistance, impaired insulin signaling, β-cell dysfunction, impaired glucose and lipid metabolism, sub-clinical inflammation, and increased oxidative stress." (PMID 33918509, 2021). "After adjusting for age group, educational status, and knowledge of insulin self-administration as confounding factors, educational status, knowledge of diabetes and insulin self-administration, and duration of insulin use were significantly associated with hypoglycemia at a P-value <0.05." (PMID 34690922, 2021). "In addition, research has shown that direct communications between a diabetes patient and a clinician via Skype appeared to help supported self-adjustment of insulin dosage." (PMID 34682621, 2021). "Indeed, antioxidant enzymes in pancreatic cells play critical roles in mediating IR, insulin secretion, and the late-stage complications of diabetes." (PMID 34206460, 2021). "Applying insulin in the treatment of diabetes mellitus is a well-known form of therapy." (PMID 34200384, 2021). "Finally, the use of the latest diabetes technological advances, such as insulin pumps and CGM devices, has greatly advanced the ability to manage glucose levels around physical activity." (PMID 34501920, 2021). "Medication intake and perceived barriers (mean ± SD) stratified by diabetes type and insulin use." (PMID 36994341, 2021). "Furthermore, poor diabetes control, the use of insulin treatment, and increases in HOMA-IR and HbA1c levels were inversely associated with cognitive functioning." (PMID 34777250, 2021). "In addition, gender, body mass index, insulin treatment, family history of diabetes, history of cardiovascular disease were significant effect modifiers for the association between PA and RPC." (PMID 33444338, 2021). "MetS group also showed higher values in parameters included as a definition of MetS, such as frequency of the usage of antihypertensive agents, hypolipidemic agents, and oral diabetes drugs/regular insulin, higher waist circumference, and higher systolic and diastolic blood pressures." (PMID 35052521, 2021).
diabetes (continued). "Clinical features that raise suspicion for mitochondrial diabetes include multi-organ involvement, elevated serum lactate levels, a more rapid progression to insulin therapy and the earlier onset of diabetes-related complications compared to individuals with T2D." (PMID 34205752, 2021). "Alcohol is suggested to lower levels of inflammation markers and endothelial dysfunction, increase insulin sensitivity, increase HDL cholesterol concentrations, which, for example, may lower the risk of type 2 diabetes mellitus and possibly also GDM." (PMID 34233654, 2021). "Insulin restriction (reducing or omitting insulin) is diabetes-specific disordered eating behavior of controlling weight by purposeful underdosing or complete omission of the required insulin in order to excrete glucose through the urine (purge calories via glucosuria)." (PMID 34638531, 2021). "Different types of technology (eg, glucose monitoring systems, insulin pens, insulin pumps, closed-loop systems, mobile health apps, telemedicine, and electronic medical records) may help to improve diabetes treatment." (PMID 33759789, 2021). "The background description could also be kept short in cases where the patient was suffering from multimorbidity:Discharge summary 8:“63-year-old man, with known diabetes mellitus, insulin treated from (year)." (PMID 33413305, 2021). "Interestingly, adult NOD/ToIβ mice in which ΔNIκBα was induced in insulin-expressing cells during the embryonic period (E11–P1) had a significantly higher incidence of diabetes at 35 weeks (83%) compared to the control group (52%)." (PMID 33414444, 2021). "A possible explanation for a positive family history of diabetes may be insulin resistance and, consequently, exuberant elaboration of insulin." (PMID 34583764, 2021). "Taken together, the risk group we identified for the population with diabetes and COVID-19, i.e. older individuals with comorbid conditions and using insulin, might simply reflect severity of diabetes or poor health conditions per se." (PMID 33907860, 2021). "However, further studies are needed to understand the molecular basis of adipose tissue response to insulin as it is highly relevant to the pharmacotherapy of diabetes and weight gain." (PMID 34203830, 2021). "Patients were afraid of shortages in diabetes medication and reported problems with the contact-free transmission of therapy data to their diabetology practice and uncertainty about how to adjust insulin requirements under changing everyday conditions." (PMID 35146280, 2021). "In addition to medication such as insulin and antidiabetic drugs, surgery is an important treatment strategy for diabetes." (PMID 33613101, 2021). "Looking at the sex- and age-adjusted estimates individually, currently taking insulin (95% CI: −0.992 to −0.302) and duration of diabetes (95% CI: −0.075 to −0.026) were predictors for a lower quality of life while complications was not (95% CI: −0.840 to 0.029)." (PMID 33651277, 2021). "Disruptions to this glucose stimulated insulin secretion pathway occur in diabetes." (PMID 33939712, 2021). "In RCTs, MHT was associated with lower levels of fasting glucose and fasting insulin and reduced insulin resistance in women with and without diabetes mellitus, and a decreased risk of developing diabetes mellitus (RR 0.70, 95% CI 0.60 to 0.90)." (PMID 34339416, 2021). "Finally, she was referred to our tertiary diabetes department due to persistent poor glycemic control despite these treatments including intravenous insulin therapy." (PMID 34281618, 2021). "Further research is needed to examine the interaction between diabetes duration and insulin use." (PMID 34424924, 2021). "As expected, other genes (PCK2, DOC2B) pointed at insulin regulation, diabetes and obesity." (PMID 33510859, 2021). "In this regard, dietary flavonoids may enhance insulin sensitivity in diabetes by acting as insulin sensitizers." (PMID 34208379, 2021).
diabetes (continued). "It looks like diabetes mellitus type 2 could also be developed this way in the form of impaired insulin metabolism and disruption of the normal functioning of the pancreas." (PMID 34883749, 2021). "These include becoming easily frustrated in situations such as delayed or inappropriate use of insulin therapy and significant deficits in diabetes knowledge, indicating that many could benefit from more individualised management." (PMID 34136579, 2021). "Patients bearing autosomal dominant diabetogenic mutations in the INS gene develop a syndrome referred to as Mutant INS gene-induced Diabetes of Youth {MIDY; alternative designations include non-autoimmune type 1 diabetes, MODY10 (OMIM #613370), as well as other names }." (PMID 34245311, 2021). "This cohort study uses Medicare claims data to assess the incidence of sulfonylurea and/or insulin treatment deintensification after an episode of severe hypoglycemia requiring an emergency department visit or hospitalization among older adults with diabetes." (PMID 34726745, 2021). "Subjects with diabetes showed improvements in insulin sensitivity despite lower meal-induced insulin secretion, increased insulin-sensitizing hormone FGF21, a 1.7-fold increment in mitochondrial activity, lower fasting plasma BCAA levels, and the expression of mTOR." (PMID 34209599, 2021). "The FDA approved NPH insulin for the control of diabetes mellitus type 1 as well as type 2." (PMID 34200384, 2021). "Therefore, accurate measurement of insulin level in blood is of great value for early diagnosis and basic research of hyperglycemia and diabetes." (PMID 34863202, 2021). "PTPN1 is a risk-factor gene linked to diabetes and obesity, which has a direct involvement in the insulin and leptin signaling pathways, and that mice lacking this gene were resistant to weight gain and intolerant to glucose." (PMID 34220925, 2021). "Participants self-reported diabetes diagnosis, physical activity, sedentary time, fruit and vegetable consumption, any special diet/program for diabetes, whether they were taking insulin for diabetes and number of years of education." (PMID 34789208, 2021). "Therefore, an appropriate metabolic response upon immunologic challenge was limited, resulting in some diabetes patients requiring substantial amounts of insulin during severe infections." (PMID 33761466, 2021). "In addition, at baseline, 72.3% of the participants were receiving insulin and 39.9% were receiving an oral diabetes medication." (PMID 34028550, 2021). "The ROS, to accrue from oxidative stress, could facilitate type-2 diabetes mellitus by decreasing pancreatic insulin production and increasing insulin resistance." (PMID 33917819, 2021). "In sum, specific monoclonal antibodies blocked the capture of insulin peptides released from the islets; such a process may translate into immunoinhibitory effects that dampened the penetrance of diabetes." (PMID 33822842, 2021). "Insulin therapy may be essential for many patients during the course of type 2 diabetes mellitus (T2DM)." (PMID 33776906, 2021). "In addition, there is the necessary equipment and facilities to rapidly diagnosis diabetes, especially given levels of misdiagnosis among a number of LMICs, as well as enable patients to routinely monitor their insulin levels at home to prevent complications." (PMID 34249838, 2021). "The disease is associated to a pro-inflammatory state with a moderate excess in the production of cytokines such as IL-6, IL-1 or tumor necrosis factor (TNF), which hinder the interaction of insulin with its receptor and contribute to insulin resistance and diabetes." (PMID 33578998, 2021). "Although loss of insulin production was understood to be a factor in the development of diabetes by the early 1920s, it was at first not clearly established that a loss of functional β cells led to insufficient insulin release." (PMID 34822454, 2021).